LILRB2 (leukocyte immunoglobulin like receptor B2)
Diseases named in the same sentence as LILRB2 in open-access papers (continued):
Sharing a sentence is not in itself a finding about the gene and the disease.
tumor (97 papers, 2014 to 2025). "In non-small cell lung cancer (NSCLC), LILRB2 is highly expressed on tumor-associated macrophages (TAMs) and dendritic cells, contributing to immune suppression and poor antigen presentation." (PMID 40821795, 2025). "Deletion of the CST3 gene, which encodes cystatin C, in host mice and tumor cells impaired tumor growth, whereas its overexpression accelerated cancer progression in LILRB2 and LILRB5 transgenic mice." (PMID 41233352, 2025). "LILRB2 promotes the polarization of TAMs toward M2-like phenotypes, which are associated with immune suppression and tumor progression." (PMID 40860159, 2025). "Highly expressed HLA-G and highly inhibited LILRB2 implicated involvement of immune tolerance or anti-tumor immune escape." (PMID 38450191, 2024). "A series of studies have shown that in a variety of tumours, such as colon cancer, non‐small cell lung cancer, and hepatocellular carcinoma, overexpressed LILRB2 was associated with a poor prognosis." (PMID 36748687, 2023). "Another study showed that LILRB2 inhibits the function of CD8 + T cells, while downregulating the expression of LILRB2 impaired the recruitment of tumor-associated macrophages." (PMID 36853330, 2023). "In this study, LILRB1 was shown to be more prevalent than LILRB2 in both healthy donor-derived macrophages and tumor-associated macrophages." (PMID 35865547, 2022). "Research has also discovered that LILRB2 expressed on tumor-associated myeloid cells inhibited the activation of SHP1/2, AKT and STAT6, leading to restraint of the function of M1-like macrophages and promotion of the function of M2-like macrophages." (PMID 35321724, 2022). "These cells, which were overexpressed CaMK1, cause tumor cell growth similar to levels of untreated A549 cells indicating that CaMK1 rescued the LILRB2 deficiency." (PMID 26056041, 2015). "This suggests that LILRB2 may function as a myeloid immune checkpoint, reshaping the tumor-associated myeloid landscape and eliciting anti-tumor immunity." (PMID 38342925, 2024). "Specifically, in cancer, LILRB2 was reported as a potentially myeloid immune checkpoint that regulates tumor-associated myeloid cells and provokes immune reaction against the development of tumor." (PMID 35938019, 2022). "Interestingly, LILRB2 antagonism was suggested to reprogram tumor-associated myeloid cells, to enhance pro-inflammatory responses and to promote antitumor effects of T cell immune checkpoint inhibitors." (PMID 36389667, 2022). "More recently, tumor-derived LILRB2 was implicated in inducing T cell senescence." (PMID 35076022, 2022). "According to previous research, LILRB2 contributes to immune suppression and tumor advancement in malignancies such as acute myeloid leukemia and non-small cell lung cancer." (PMID 41383852, 2025). "Here, we establish a direct link between oligomeric cystatin C—a cysteine cathepsin inhibitor and a well-characterized amyloidogenic protein—within the tumor microenvironment and the immune inhibitory receptors LILRB2 and LILRB5 on myeloid cells." (PMID 41233352, 2025). "LILRB2 was significantly upregulated in endometrial cancer, where it predicted poor prognosis and functionally promoted tumor cell proliferation, colony formation, and migration." (PMID 40860159, 2025). "LILRB1 and LILRB2 are expressed in various tumor types and are recognized as immunosuppressive markers within the tumor TME." (PMID 41050411, 2025). "Abnormal expression levels of LILRB2 and APE1 are associated with age, tumor diameter, TNM stage, and LNM in CRC patients." (PMID 41383852, 2025). "Compared with isotype control treatment, blockade of LILRB2 significantly delayed SK-MEL-5-hcystatin C tumor growth." (PMID 41233352, 2025). "Previous studies have shown that LILRB2 functions as an immunosuppressive protein to induce T-cell senescence and suppress tumor immunity." (PMID 36853330, 2023).
tumor (continued). "In macrophages, ANGPTL8 binding to LILRB2/PIRB stimulates macrophage polarization to the M2 phenotype to suppress the antitumor immune response within the tumor microenvironment, allowing tumorigenic HCC cells to escape immune surveillance." (PMID 37188659, 2023). "Umiker and colleagues demonstrated that the blockade of LILRB2 with JTX-8064 in different tumour types reprogrammes macrophages and DCs by inhibiting HLA I ligand binding." (PMID 38022598, 2023). "Engagement of LILRB1 and LILRB2 with its ligand HLA-G inhibits immune activation, resulting in indirect promotion of tumor development." (PMID 35321724, 2022). "LILRB2 expression is largely restricted to myeloid cells, making it an attractive target for modifying the tumor myeloid cell landscape." (PMID 34638388, 2021). "Using shRNAs to inhibit LILRB2 expression, they demonstrated that the cultured A549 cancer cells were significantly slower in proliferation and had an increased cell death suggesting that LILRB2 overexpression enhances tumor growth." (PMID 34276685, 2021). "The myeloid cells within the tumor core are also the main source of LILRB2 expression, offering a selective target for reprogramming a significant cell population for maintaining tumoral viability." (PMID 32983100, 2020). "To understand the mechanism by which ANGPTL2/LILRB2 controls tumor growth, we analyzed apoptosis and the cell cycle status of A549 cells knockdowned with shRNA targeting LILRB2 or with a control shRNA." (PMID 26056041, 2015). "Our results provide intriguing clues that ANGPTL2/LILRB2 triggers several signaling pathways to support the stemness (self-renewal and differentiation) and migration ability for both normal stem cells and tumor cells." (PMID 26056041, 2015). "Consistent with this tumor-promoting phenotype, flow cytometry analysis revealed that B16-F10-hcystatin C overexpression significantly increased the proportion of LILRB2+ myeloid cells among total myeloid cells in LILRB2KI mice, indicating a more immunosuppressive TME." (PMID 41233352, 2025). "LILRB2 is known to inhibit immune cell activity and modulate the tumor immune microenvironment through its interaction with ligands such as HLA-G, angiopoietin-like protein 2, and semaphorin-4A, thereby promoting tumor cell proliferation and metastasis." (PMID 41383852, 2025). "Specifically, LILRB2 may characterize a myeloid immunosuppression–dominant tumor microenvironment within microsatellite-stable (MSS) subtypes, offering a potential therapeutic target for overcoming the limited efficacy of immunotherapy in this group." (PMID 41383852, 2025). "Importantly, anti-LILRB2 treatment significantly delayed B16-F10-hcystatin C tumor progression in LILRB2KI mice." (PMID 41233352, 2025). "Tumor expressing HLA-G family members bind to both LILRB1 and LILRB2 receptors suggesting that monotherapy blockade of either LILRB1 or LILRB2 alone could lead to tumor escape mechanisms." (PMID 39199672, 2024). "Expression of LILRB2 on tumours correlates with higher levels of IL-10." (PMID 38022598, 2023). "Recently, studies have shown that LILRB2 is also enriched in tumor cells." (PMID 36853330, 2023). "Additionally, LILRB2 blockade combined with anti-PD-L1 mAb enhances the phagocytosis of TAMs and increases their anti-tumor effects in transgenic mice, which can express human LILRB2 on myeloid cells." (PMID 35978372, 2022). "Furthermore, LILRB2 blockade in preclinical NSCLC models reduced granulocytic myeloid-derived suppressor cell (MDSC) and Treg infiltration and skewed tumor-associated myeloid cells toward a more inflammatory immune phenotype, with enhanced antitumor activity." (PMID 35076022, 2022). "PIR-B is a key regulator for maintaining the M2 phenotype of tumor-infiltrating MDSCs, and we demonstrated for the first time that blockade of LILRB2 induces differentiation MDSCs into the M1 type of macrophages, altering the tumor microenvironment towards anticancer responses." (PMID 35757769, 2022).
tumor (continued). "Blocking of LILRB2 promotes anti-tumor immunity of myeloid cells." (PMID 36153593, 2022). "While LILRB1 and LILRB2 recognize the conserved α3 and B2M domains in most HLA haplotypes, HLA-G has emerged as an interesting binding partner due to its more restricted expression on tumor cells." (PMID 35865547, 2022). "ATM, SIRPA, and LILRB2 are potential targets in tumor immunotherapy." (PMID 33868359, 2021). "Additionally, we have shown that targeted therapy against LILRB2 on tumor-infiltrating myeloid cells can reverse their suppressive fate initiated by the malignancy and diminish lung cancer tumor burden in murine models." (PMID 32983100, 2020). "Moreover, the top three downregulated pairs in LUAD tumor cells were HLA-B and its ligand LILRB2, GAS6-AXL, and VIM-CD44." (PMID 32549766, 2020). "HLA-B and its ligand LILRB2 were found to be downregulated in LUAD tumor cells." (PMID 32549766, 2020). "We also found that some stromal cells were positive for the LILRB2 (SFigure 1B-1C), which indicated the tumor microenviroment might be involved in the cancer development." (PMID 26056041, 2015). "Most strikingly, in vivo engraftment experiments clearly revealed that the tumor forming ability of A549 cells was almost totally abolished by knockdown of LILRB2 with shRNA4; tumor sizes and weights were much smaller than those in mice given cells knockdowned with the scramble control." (PMID 26056041, 2015). "Simultaneously, oligomeric cystatin C binds to the inhibitory receptors LILRB2 and LILRB5 on myeloid cells, thereby increasing their immunosuppressive activity and contributing to tumor progression." (PMID 41233352, 2025). "The expression of SIRPA, LILRB1, LILRB2, Siglec1, Siglec7, Siglec9, PDCD1, CD163 and MARCO are preferentially expressed on Mono01, Mono02 and Macro03, suggesting their tumor-promoting roles." (PMID 40755770, 2025). "Our findings provide a potential mechanistic explanation for this phenomenon: amyloid proteins activate LILRB2 and LILRB5 inhibitory receptors on myeloid cells, establishing an immunosuppressive TME that supports tumor growth and metastasis." (PMID 41233352, 2025). "By interacting with the LILRB1, LILRB2, KIR3DL1 and CD64 receptors, it enhances anti-tumor activity." (PMID 39199672, 2024). "Other immune checkpoints that have played significant roles are CD276, leukocyte immunoglobulin-like receptor subfamily B member 2 (LILRB2), and CD47, which were upregulated in CSCs and led to a weakened or damaged host anti-tumor response." (PMID 39335624, 2024). "LILRB2 is Leukocyte immunoglobulin-like receptor subfamily B member 2 (also known as ILT-4, immunoglobulin-like transcript 4) is a tumor immune checkpoint molecule." (PMID 38450191, 2024). "Innate ICIs achieve anti-tumor purposes by targeting checkpoints such as SIRPα, TIGIT, PVRIG, LILRB2, NKG2A, LAG-3, TIM-3, VISTA and CD32B." (PMID 37510993, 2023). "Subsequently, we attempted to perform immunohistochemistry (IHC) staining for NRGs (CYBB, ITGB2, ITGAM, LILRB2, TLR2, and TLR7) in kidney sections from ANCA-GN patients and age- and sex-matched ccRCC patients with adjacent non-tumor tissues." (PMID 37465687, 2023). "LILRB2/PIRB is an inhibitor of inflammation and autoimmunity, and LILRB2 blockade with antagonizing antibodies increases tumor cell death and the killing activity of cytotoxic T lymphocytes." (PMID 37188659, 2023). "This study aims to investigate the role of LILRB2 in GBM and determine how LILRB2 in sEVs regulates tumor immunity." (PMID 36853330, 2023). "However, inconsistent with the results of other tumours, high expressions of LILRB2 and LILRB4 were associated with better clinical outcomes in our study, while other studies showed that patients with high expressions of LILRB2 and LILRB4 predicted worse clinical outcomes." (PMID 36748687, 2023).
tumor (continued). "HLA-G molecules are ligands for the inhibitory immune receptors, LILRB1 and LILRB2 (also known as ILT2 and ILT4), and are frequently expressed by solid tumors, therefore, anti-HLA-G CAR-NK can both target tumor cells and relieve immunosuppression." (PMID 37388731, 2023). "Functionally, HLA-G has comprehensive immunosuppressive properties exerted in multiple steps to weaken anti-tumor immune responses by acting on immune cells through its inhibitory receptors: ILT2(CD85j/LILRB1), ILT4(CD85d/LILRB2), and KIR2DL4(CD158d)." (PMID 32670296, 2020). "For instance, an autocrine signaling between ANGPTL2 and its receptor LILRB2 was able to induce early EMT and tumor progression in preneoplastic pancreatic ductal cells." (PMID 32410376, 2020). "Furthermore, LILRB2 can interact with HLA-G in the TME, promoting myeloid cell tumor proliferation and increasing tumor immune evasion." (PMID 41050411, 2025). "Preclinical models show that LILRB2 blockade reprograms myeloid cells to a pro-inflammatory phenotype, enhances MHC-II and CD86 expression, and synergizes with anti–PD-1 therapy to improve T cell infiltration and tumor regression." (PMID 40821795, 2025). "Similarly, the combination therapy was more effective at reducing the tumour burden against human NSCLC (A549) cells in vivo, which was due to reprograming of human myeloid cells by anti-LILRB2." (PMID 40385641, 2025). "Although LILRB2 and APE1 have been independently identified as regulators of tumor immunity and DNA repair, respectively, potential crosstalk or synergistic regulation between them in CRC remains unclear." (PMID 41383852, 2025). "Furthermore, we isolated different components of the GL261 culture medium and found that LILRB2 in GBM cells can be delivered through sEVs to other cells, such as tumor cells and immune cells." (PMID 36853330, 2023). "The HLA-G molecule can interact with leukocyte receptors (e.g., ILT-2 [LILRB1/CD85j], ILT-4 [LILRB2/CD85d], and KIR2DL4 [CD158d]), mostly on CD8+ T and natural killer (NK) cells, inducing inhibitory cytotoxic responses, facilitating tumor cell proliferation and spread." (PMID 37569841, 2023). "Like LILRB2, LILRB4 has been reported to control NSCLC pathogenesis, enhancing widespread NSCLC cell invasion and tumor angiogenesis, and may serve as an alternative strategy for NSCLC treatment." (PMID 35076022, 2022). "As a result, GPR84, NCF2, HK3, LILRB2, and CCL18 significantly affected the overall survival (OS) of GBM patients (multivatiate Cox p < 0.05), of which the protein level of GPR84 and NCF2 was significantly increased in the tumor core region." (PMID 36177003, 2022). "Additionally, when combined with anti-PD-L1, LILRB2 blockade could remodel the TME and provoke anti-tumor immunity." (PMID 37510993, 2023). "Furthermore, HLA class I deficient B6-F10 tumor growth has been reported to be suppressed in immunodeficient non-obese diabetic (NOD)-scid IL2Rgammanull mice, although LILRB2 gene deficiency did not enhance CD47 disruption-mediated cancer cell phagocytosis in vitro." (PMID 34638388, 2021). "While the anti-LILRB2 antibody was not effective, the anti-LILRB1 antibody enhanced ADCP considerably, but strictly required simultaneous CD47 blockade and the presence of a tumor targeting CD20 antibody to become effective." (PMID 36389667, 2022).
cancer (49 papers, 2009 to 2026). A tumor composed of atypical neoplastic, often pleomorphic cells that invade other tissues. "However, the functional role and underlying mechanisms of LILRB2 in cancer stem cells require further investigation." (PMID 40860159, 2025). "We demonstrated that oligomeric cystatin C enhances the immunosuppressive activity of myeloid cells by engaging LILRB2/5 inhibitory receptors, thereby suppressing T-cell function and promoting cancer progression." (PMID 41233352, 2025). "Cancer stem cells in head and neck squamous cell carcinoma are key drivers of multidrug resistance, metastasis, recurrence, and immunosuppression, with LILRB2 expression notably upregulated in these cells." (PMID 40860159, 2025). "HLA-B57:01:01 has a similar profile as HLA-B27 by binding to LILRB1, LILRB2 and KIR3DL1 receptors, both LILRB1 and LILRB2 checkpoint receptors are of wide clinical interest in cancer immunotherapy." (PMID 39199672, 2024). "Blockade of LILRB2 has been demonstrated to reduce cancer cell proliferation, migration and invasion of cancer cells." (PMID 38022598, 2023). "The LILRB family, specifically LILRB2, is integral to the immune evasion strategies of cancer cells." (PMID 37965573, 2023). "In vitro, LILRB2 inhibition involving NSCLC cancer cell line A549 leads to significant decrease in cancer migration and proliferation potential." (PMID 36031601, 2022). "Upregulation of either LILRB1 or LILRB2 in macrophages has shown an evasion mechanism for cancer cells against phagocytosis." (PMID 32292502, 2020). "Another potentially important checkpoint in cancers is LILRB2." (PMID 34276685, 2021). "Moreover, CST3 expression was significantly positively correlated with the expression of LILRB2 or LILRB5, particularly LILRB2, in most of these cancer types, although these observed Spearman’s rho values were within the range typically considered weak correlations." (PMID 41233352, 2025). "LILRB2, an MHC-binding protein rich in TAMs, interacts with MHC class I molecules, which cancer cells often downregulate to dodge T cell recognition." (PMID 37965573, 2023). "Similarly, ANGPTLs have been demonstrated to play crucial roles in lipid metabolism and angiogenesis, and our previous study showed that LILRB2 inhibits differentiation and promotes self-renewal of HSCs and LSCs; however, the function of LILRB2 in cancer progression remains unclear." (PMID 26056041, 2015). "Given their potential to inhibit T cell proliferation, LILRB2 and LILRB4 have been studied in the context of allograft tolerance during transplantation and during cancer." (PMID 19860908, 2009). "High-level expression of the receptors LILRB2 (ILT4) and LILRB4 (ILT3) is a feature of tolerogenic antigen presenting cells and has been observed in cancer and transplant situations." (PMID 19860908, 2009). "LILRB1 and LILRB2 expressed in macrophage subsets were found to interact with the nonclassical human leukocyte antigen HLA-F expressed in cancer cells." (PMID 39669575, 2024). "HLA-G and its receptors are considered as a new immune checkpoint and potential targets for cancer immunotherapy, and several antibodies targeting HLA-G, LILRB1, or LILRB2 are currently in clinical trials for cancer treatment." (PMID 39237366, 2024). "Furthermore, HLA-F was upregulated in cancer cells from the S components, which was shown to be correlated with the upregulation of LILRB1/LILRB2 in macrophages." (PMID 35874770, 2022). "H1299 and A549 cells highly expressed LILRB2 compared to the other cancer cell lines evaluated and to normal lung epithelial cells, BEAS-2B cells." (PMID 26056041, 2015). "Conversely, higher expression of these markers was associated with better survival rates in the SKCM cohort Consequently, although HLA-A/B/C and LILRA1/LILRA3/LILRB2 were commonly observed in non-responder TIMs, their association with post- ICB patient survival appears to be cancer-specific." (PMID 39034339, 2024).
cancer (continued). "Thus, LILRB2 mAb-mediated blockade demonstrates a capacity for TAM reprogramming, in addition to potentially suppressing ‘don’t eat me’ signaling derived from interactions with HLA class I on cancer cells." (PMID 34638388, 2021).